IL17RB (interleukin 17 receptor B)
Diseases named in the same sentence as IL17RB in open-access papers (continued):
Sharing a sentence is not in itself a finding about the gene and the disease.
tumor (continued). "Our results suggest that the expression of IL17RB may influence the anti-tumor functions of CD4 Tem, memory B, and activated NK cells, and IL17REL may influence the anti-tumor functions of CD8Tcm, memory B cells, M1 macrophages, and Helper T cells in HPV-positive HNSCC tumors." (PMID 37111458, 2023). "Moreover, we also find that two genes encoding IL17 receptor family members, IL17RB and IL17REL, are associated with improved prognosis and may modulate the anti-tumor activity of memory B, NK cells, and T cell subsets in HPV-infected HNSCC patients." (PMID 37111458, 2023). "Next, we asked whether anti-IL-17RB response affects tumor growth and its subsequent dissemination." (PMID 35214622, 2022). "Thus, we conclude that high expression of IL-17RB in CSCs promotes cancer initiation, propagation, metastasis, and recurrence, and IL-17B and IL-17RB form a positive feedback loop that further amplifies the IL-17B/IL-17RB signaling cascade in the tumor environment." (PMID 33649532, 2021). "Thus, IL-17B/IL-17RB signaling establishes a feedback loop between tumor cells and PSCs." (PMID 34771503, 2021). "Likewise, chemokines might also be secreted by tumor-infiltrating cells as a result of stimulation of IL-17RB-expressing stromal, and might contribute to macrophages and endothelial cell recruitment to promote cancer progression." (PMID 32373132, 2020). "Thus, both direct IL-17RB signaling in the tumor cells and indirect IL-17RB signaling in cells present in the tumor microenvironment, such as MSCs, might contribute to promote tumor proliferation." (PMID 32373132, 2020). "Moreover, IL-17RB-mediated secretion of soluble factors will ultimately reshape the tumor microenvironment toward a macrophage-enriched infiltrate that might impair the anti-tumor immune response and favor resistance to treatments." (PMID 32373132, 2020). "Consistent with the expression of Il13ra1 and Il17rb on tuft cells, IL25 or IL13 stimulation of tumor organoids increased their size, while treatment of organoids with an α-IL25 neutralizing antibody resulted in reduced organoid growth." (PMID 37898600, 2023). "When comparing the gene profile of CAFs from two tumor foci for each one of these cases, we only found significant differences between CAFs populations for FGF10, IL17RB, and MMP2, evidencing a little variability within the multifocal PCa tumor focus." (PMID 35885510, 2022). "Depletion of IL-17RB resulted in inhibited colony formation and retarded MDA-MB-361 tumor growth in mice." (PMID 35954312, 2022). "We found that IL-17RB was highly expressed in GC-CSC-like cells, and that IL-17B promoted the sphere-formation ability of CSCs in vitro and enhanced tumor growth, invasion and stmness in vivo." (PMID 33649532, 2021). "PDAC cells treated with CM from IL-17RB OE PSCs showed a trend towards increased OCR compared with control CM and a significant increase of the OCR compared with naive tumor cells." (PMID 34771503, 2021). "We measured the oxygen consumption rate (OCR) of human Panc-1 tumor cells cultured alone or with CM from IL-17RB OE (and from the respective VEC OE control), as well as CM from IL-17RB KD PSCs (and VEC KD control)." (PMID 34771503, 2021). "RIL-17B treatment promoted the tumorigenic frequency and tumor volume in HGC-27-shControl than PBS treatment in the same dilution concentration of cells, while the knockout of IL-17RB in HGC-27 cells obviously reversed the effection of rIL-17B pro-tumorigenic." (PMID 33649532, 2021). "Morphologically clearly identifiable tumor cells (white arrows), as well as α-SMA positive stromal cells (black arrows), expressed IL-17RB." (PMID 34771503, 2021). "CM of IL-17RB OE PSCs induced CXCR4 expression, contributing to tumor growth, invasion, and metastasis." (PMID 34771503, 2021). "We detected the expression of IL-17RB, Lgr5, and CD90 in single tumor cells purified from GC tissues through flow cytometry." (PMID 33649532, 2021).
tumor (continued). "Knockdown of IL-17RB, MUC1 and/or MUC4 also suppresses expression of stemness-related markers, such as SOX2, Nanog, Oct-4, and CD44, and inhibited tumor sphere formation." (PMID 33082357, 2020). "Depletion of IL-17B or IL-17RB by shRNA or treatment with anti-IL-17B or anti-IL-17RB antibodies reduces CFPAC-1 and BxPC3 pancreatic cell line colony formation, invasion, tumor growth, and metastasis in xenograft models." (PMID 32373132, 2020). "For further confirmation, we sorted tumor macrophages (CD45+CD11b+F4/80+Gr-1-), tumor-infiltrating CD4+ (CD45+CD4+CD11b-), and CD45- cells, and then examined the mRNA level of IL-17RB in these cells." (PMID 27909985, 2017). "Although little is known regarding the role of IL17RB in MM, a recent study observed that IL-17 produced by TH17 cells promotes MM cell growth, colony formation and tumor growth in vivo via IL17R." (PMID 23285118, 2012). "Moreover, the IHC results showed higher levels of IL17RB and CREB1 expression in tumours of mice overexpressing CHDH." (PMID 40928004, 2025). "We hypothesised that CHDH activates CREB1 by promoting the expression of IL17RB, which may reveal a novel mechanism by which CHDH promotes tumour progression." (PMID 40928004, 2025). "Therefore, we demonstrated that the therapeutic use of C:IRIS, which showed great anti-tumor effects through disruption of ERK1/2 activation, moves the critical signal transduction event downstream to IL-17RB." (PMID 35214622, 2022). "The clinical parameters including age, gender, tumor subtype, T value, N value, tumor stage and grade are not significantly correlated with IL-17RB, MUC1, or MUC4 expression." (PMID 33082357, 2020). "To further address whether Il‐17rb contributes to tumor growth and metastasis, we used a RNA‐guided CRISPR‐Cas9 system to delete Il‐17rb in 4T1 cells for in vivo tumor growth and lung colonization assays." (PMID 28993429, 2017). "Although we here confirmed that IL-17RB expression is much higher in tumor cells than in non-transformed cells, we were unable to detect IL-17E mRNA in MCF10A cells." (PMID 26154409, 2015). "IL-25, a proinflammatory cytokine, secreted by normal mammary epithelial cells and induces apoptosis of tumor cells via IL-25R (IL-17RB) highly expressed in tumor cells and barely expressed in normal epithelial cells." (PMID 26313265, 2015). "In addition, proteins observed to be absent in tumor scaffolds in the LKB1 overexpressing cell line included those associated with the adipose matrix (COL6A2) and regulators of adipogenesis (IL17RB and IGFBP4), suggesting a role for LKB1 in tumor-mediated adipogenesis." (PMID 35755802, 2022). "Wen-Hwa Lee and co-workers also clearly indicated the critical roles of IL-17B/IL-17RB signaling in cancer progression.However, it is unclear whether IL-17B exhibits potential effects on MSC in the tumor microenvironment and contributes to tumor progression." (PMID 28145881, 2017). "However, our studies showed that tumor macrophages in the MMTV-PyMT tumor model did not express IL-17RB and thus cannot directly respond to IL-25, similar to the alternatively activated macrophages as reported." (PMID 27909985, 2017). "Unlike the previous in vitro studies, we noticed that the tumor cells in the MMTV-PyMT tumor model did not express IL-17RB – the receptor for IL-25, and thus could not respond directly to IL-25 treatment." (PMID 27909985, 2017). "Interestingly, IL-17RB was selectively expressed by intra-tumor CD4+ T cells, but not CD8+ T, NK, γδ T cells or macrophages." (PMID 27909985, 2017). "In addition, some proteins expression levels were not positive correlation with the expression level of IL-17RB, it may be related to individual differences in tumor patients." (PMID 27146881, 2016). "We found that only tumor-infiltrating CD4+ T cells, but not CD8+ T, macrophages or tumor cells express IL-17RB – the receptor for IL-25." (PMID 27909985, 2017).
tumor (continued). "Moreover, administration of a neutralizing anti-IL-17RB antibody (50 μg/injection twice a week) did not affect MCF7-hIL-17B and MDA-MB-468-hIL-17B tumor progression in the absence of paclitaxel treatment." (PMID 29371916, 2017).
cancer (63 papers, 2014 to 2025). A tumor composed of atypical neoplastic, often pleomorphic cells that invade other tissues. "Upon activation by upstream interleukins, IL-17RB facilitates downstream signal transduction, triggering pathways implicated in cancer progression, including NF-κB, MAPK, and STAT3." (PMID 40630198, 2025). "Elevated IL‐17RB expression in cancer cells was associated with malignant growth in mouse xenograft assay." (PMID 28993429, 2017). "Overexpression of IL-17RB in lung cancer tissue significantly increases cancer cell invasion, migration, and metastasis." (PMID 39906741, 2024). "For example, in mice, IL-17B signaling via IL-17RB facilitates cancer cell survival, invasion, proliferation, and metastasis, whereas in humans, high expression of IL-17B and IL-17RB is linked to a poorer prognostic outcome in BC sufferers." (PMID 38239641, 2023). "The survival, proliferation, and migration of cancer cells are directly promoted, and resistance to conventional chemotherapy drugs is induced through the IL-17RB/IL-17B signaling pathway." (PMID 37771430, 2023). "IL-17B signaling directly promotes the proliferation and migration of cancer cells through IL-17RB and induces resistance to traditional chemotherapy drugs." (PMID 37686343, 2023). "Previously, we reported the findings that interleukin 17 receptor B (IL-17RB) signaling contributes to cancer survival, proliferation and metastasis upon binding to its cognate ligand IL-17B." (PMID 35214622, 2022). "Previously, we identified an IL-17RB targeting mAb which intercepts IL-17B/IL-17RB signal transduction and suppresses tumorigenesis in many types of cancer." (PMID 35214622, 2022). "In this research, we developed a novel B-cell cancer vaccine by chemically conjugating the newly identified epitope from IL-17RB, an emerging cancer therapy target, and optimizing its bioactivity assisted by MALDI-TOF-MS." (PMID 35214622, 2022). "We reason that active immunity against the antigenic epitope of IL-17RB can reproduce the anti-cancer effect of mAbs with better sustainability." (PMID 35214622, 2022). "Molecularly Signal Transducer and Activator Of Transcription 3 (STAT3)-phosphorylation and hexokinase 2-expression were reduced in human cancer cells treated with CM from IL-17RB OE PSCs." (PMID 34771503, 2021). "IL-17RB was found to potentiate the metastatic and colony-forming potential of cancer cells via NF-κB, which enhanced distant metastasis." (PMID 34632244, 2021). "Since IL‐17RB is a common receptor for IL‐25 and IL‐17B, it is found that IL‐17B can induce pro‐neoplastic properties in cancer cells." (PMID 34128588, 2021). "A recent study indicated that in in vivo models, IL-17B conveyed directory through its IL-17RB and encouraged cancer cell survival to proliferation to relocation to resisting usual chemotherapeutic agents." (PMID 34336101, 2021). "For instance, in mouse models, IL-17B signaling through IL-17RB promotes cancer cell survival, proliferation, and migration, while in humans, elevated IL-17B expression has been associated with poor prognosis in patients with different cancer types." (PMID 32373132, 2020). "MUC1 and MUC4 induced by IL-17RB upregulate expression of cancer stemness-related genes, such as SOX2, Nanog, Oct-4, and surface CD44 to facilitate sphere formation." (PMID 33082357, 2020). "A decrease of the CD44-positive population was also observed in IL-17RB-knockdown cells, and downregulation of cancer stemness activity of IL-17RB-knockdown cells was also shown by the sphere formation assay." (PMID 33082357, 2020). "To explore the role of IL-17RB in the cancer stem-like property, we knocked down IL-17RB by lentivirus-based shRNA in BxPC3 cells." (PMID 33082357, 2020). "Based on the proportion of IL-17RB-expressing cancer cells, the cases can be divided into two groups: Low expression group: negative (0%) and low positive (< 10%); High expression group: high positive (≥ 10%)." (PMID 33082357, 2020).
cancer (continued). "The IL-17B/IL-17RB pathway is considered as a signaling cascade that promotes cancer cell survival, proliferation and migration." (PMID 32373132, 2020). "In mouse models, IL-17B signaling through IL-17RB directly promotes cancer cell survival, proliferation, and migration, and induces resistance to conventional chemotherapeutic agents." (PMID 32373132, 2020). "Up‐regulation of oncogenic Il‐17rb in cancer cells derived from TDLNs contributes to their malignancy." (PMID 28993429, 2017). "In the 4T1‐allografted mice, we found that Tregs‐secreted TGF‐β1 derived from TDLNs played a predominant role in the induction of IL‐17rb in cancer cells." (PMID 28993429, 2017). "In a xenograft mouse model of human pancreatic cancer CFPAC-1 cells, depletion of IL-17RB impedes cancer growth and metastasis to the liver and lungs." (PMID 29379802, 2017). "We showed that the expression of IL‐17RB was significantly up‐regulated in cancer cells and correlated with the prevalence of Tregs in the LN metastasis." (PMID 28993429, 2017). "To explore which subset of cells in the TDLNs mediated Il‐17rb up‐regulation in cancer cells, we isolated individual subset of immune cells by FACS sorter for performing the co‐culture experiment using 4T1 cells." (PMID 28993429, 2017). "Blocking this TGF‐β1/TGFR paracrine signaling abolished Il‐17rb induction as well as inhibited tumorigenic activities of cancer cells." (PMID 28993429, 2017). "In these 60 cases, the level of IL‐17RB was significantly higher in cancer cells in the LNs than those in the primary sites." (PMID 28993429, 2017). "Consistently, clinical data showed that the up‐regulation of IL‐17RB in cancer cells from LN metastases correlated with the increased prevalence of Tregs as well as the aggressive growth of tumors in mouse xenograft assay." (PMID 28993429, 2017). "The enhanced malignancy was mainly attributed to the induction of an oncogenic receptor, interleukin‐17 receptor B (Il‐17rb) in the cancer cells." (PMID 28993429, 2017). "The enhancement of cancer malignancy was due to the up‐regulation of an oncogenic receptor, Il‐17rb, by Treg‐secreted TGF‐β1." (PMID 28993429, 2017). "IL-17RB cancer cell promoted invasion, migration, and metastasis." (PMID 39906741, 2024). "They suggested that blocking IL-17RB could be an effective therapeutic target for inhibiting metastasis and cancer progression." (PMID 35248028, 2022). "Overall, the results elucidate the novel functions of IL-17B for CSCs and suggest that the intervention of the IL-17B/IL-17RB signaling pathway may provide new therapeutic targets for the treatment of cancer." (PMID 33649532, 2021). "Moreover, since IL‐17B and IL‐25 have a common receptor called IL‐17RB, it is also required to define which ligand is involved in the cancer progression." (PMID 34128588, 2021). "However, targeting IL17B/IL17RB signaling with a newly derived anti–IL17RB antibody will block cancer cell metastasis and promote survival." (PMID 34724890, 2021). "Likewise, lineage tracing in CRC cancer models has revealed preferential outgrowth of cancer cell subpopulations defined by expression of genes such as LGR5 or IL17RB or by localization at the leading edge of the tumor." (PMID 34409732, 2021). "Here, in a 4T1 model, Treg-derived TGF-β1 induced IL-17RB in cancer cells in TDLNs." (PMID 34632244, 2021). "Therefore, inhibition of IL‐17RB (IL‐25R) signaling is another therapeutic approach in cancer treatment." (PMID 34128588, 2021). "Therefore, targeting the IL-17B/IL-17RB signaling cascade is a novel approach for cancer treatment." (PMID 33649532, 2021). "Thus, by combining bioinformatics analysis of gene expression datasets and protein analysis in several independent cohorts, these studies clearly show the association between a deregulated expression of the IL-17 and/or IL-17RB and poor prognosis in many different cancers." (PMID 32373132, 2020).
cancer (continued). "Moreover, OS (p = 0.016) and DFS (p = 0.029) were significantly reduced in patients with cancers in which both IL-17B and IL-17RB were overexpressed compared with patients with cancers where only one was upregulated or where both molecules were expressed at low level." (PMID 29371916, 2017). "Thus, it is likely that Tregs in the TDLNs may be responsible for the induction of Il‐17rb in cancer cells." (PMID 28993429, 2017). "Interestingly, the total population of CD4+ T cells had the highest induction activity, suggesting that other CD4+ non‐Treg cells in the TDLNs may indirectly participate the induction of Il‐17rb in cancer cells." (PMID 28993429, 2017). "In addition to the significant roles of Il‐17rb, other genes up‐regulated in the 4T1LN cells may also have important roles in promoting cancer malignancy." (PMID 28993429, 2017). "IL-17B/IL-17RB signaling and ERK are involved in a significant pathway that enhances the invasion and migration of cancer cells." (PMID 37686343, 2023). "When IL-17RB transcriptionally upregulates the expression of MUC1 and MUC4, cancer stem-like properties and resistance to gemcitabine are further enhanced." (PMID 37686343, 2023). "These functions indicate the importance of the IL-17B/IL-17RB signaling pathway for maintaining CSC homeostasis, suggesting that the IL-17B/IL-17RB signaling pathway is a new therapeutic target for cancer treatment." (PMID 33649532, 2021). "In this work, we found IL-17RB upregulates MUC1 and MUC4 through NF-κB pathway to confer cancer cells resistance to gemcitabine." (PMID 33082357, 2020). "Nevertheless, we found that either TGF‐β1 neutralization or Tgfbr1 depletion in cancer cells significantly abolished Il‐17rb up‐regulation, suggesting a critical role of TGF‐β1 in up‐regulating Il‐17rb expression in cancer cells in the TDLNs." (PMID 28993429, 2017). "The effect of IL-17RB on PDAC proliferation and dissemination was mediated by upregulation of CCL20, CXCL1, and IL-8 cytokines through ERK signaling in PDAC cancer cells." (PMID 29379802, 2017). "A signalling cascade, IL-17B/IL-17RB pathway encourages not just cancer survival but also aids in its proliferation and relocation." (PMID 34336101, 2021). "Therefore, the results reveal novel functions of IL-17B for CSCs and implicate the importance of the IL-17B/IL-17RB signaling pathway in maintaining CSC homeostasis, suggesting that this pathway is a new therapeutic target for cancer." (PMID 33649532, 2021). "IL-17RB triggering induced CCL20/CXCL1/IL-8/TFF1 chemokine expressions via the ERK1/2 pathway, thus promoting macrophage and endothelial cell recruitment at primary sites, cancer cell invasion and survival at distant sites." (PMID 33244315, 2020). "Activated IL17B/IL-17RB signaling, which increases chemokine expression via the NF-κB and ERK1/2 pathway, promotes cancer cell invasion, macrophage and endothelial cell recruitment to the primary sites, and cancer cell survival at distant organs." (PMID 33082357, 2020). "Moreover, IL-17RB transcriptionally up-regulates expression of MUC1 and MUC4 to enhance cancer stem-like properties and resistance to gemcitabine." (PMID 33082357, 2020). "In another study, Huang and colleagues reported that Treg cells induced IL-17RB expression in BC cells by secreting TGF-β1 and activating the Smad2/4/3 signaling pathway in the tumor-draining LNs (TDLNs), thereby increasing proliferation, angiogenesis, and metastasis of cancer cells." (PMID 35248028, 2022). "Considering IL17RB is amenable in marking tuft cell-like cancer stem cells with no expression on normal stem cells, IL17RB may be a potential marker for long-term targeting." (PMID 32733896, 2020).